RNU6-317P (RNA, U6 small nuclear 317, pseudogene)
Gene: Small nuclear RNA gene on chromosome 19 (48,793,152 to 48,793,258, reverse strand). Ensembl gene ENSG00000206758.
Homologues: Orthologues: chimpanzee U6 (99% identical), rabbit U6 (90% identical), pig U6 (79% identical). Paralogues in human: RNU6-19P (93% identical), RNU6-1060P (93% identical), RNU6-15P (93% identical), RNU6-12P (92% identical), RNU6-13P (92% identical), RNU6-31P (92% identical), RNU6-32P (92% identical), RNU6-41P (92% identical), RNU6-1 (91% identical), RNU6-1024P (91% identical), RNU6-116P (91% identical), RNU6-17P (91% identical), and 1285 more.